NANOG (Nanog homeobox)
Diseases named in the same sentence as NANOG in open-access papers (continued):
Sharing a sentence is not in itself a finding about the gene and the disease.
gastric cancer (24 papers, 2014 to 2025). A primary or metastatic malignant neoplasm involving the stomach. "Zhan and colleagues also achieved similar results that TR3 promoted the stem-like properties of gastric cancer cells through the transactivation of NANOG." (PMID 32014008, 2020). "NANOGP8 is mainly responsible for NANOG expression in sphere-forming (stem cell-like) cells derived from gastric cancer cell lines regardless their differentiation status." (PMID 29689047, 2018). "Similarly, in gastric cancer, high levels of NANOG reduce overall survival and increase tumor dissemination." (PMID 39547513, 2024). "Notably, besides its role in stemness maintenance, NANOG is expressed in multiple human cancers, namely, brain, colon, prostate, and stomach cancers." (PMID 32197405, 2020). "The homology cassette transcription factor NANOG is essential for embryonic stem cell renewal, and the related pseudogene NANOGP8 is a major contributor to NANOG-induced effects on gastric cancer." (PMID 38952556, 2024). "Specifically, gastric cancer cells with enhanced BATF2 expression exhibited significantly lower levels of the cancer stem cell markers CD44, NANOG, and SOX2 than the control cells." (PMID 39629124, 2024). "In the case of gastric cancer cells, we newly screened the levels of NANOG protein and selected MKN28 as a representative NANOGhigh gastric cancer cell." (PMID 37165076, 2023). "For example, poor survival is associated with high expression of OCT4 (protein encoded by POU5F1 gene) in gastric cancer, high expression of NANOG in lung and breast cancer, or high expression of SOX2 in gastric cancer." (PMID 32664372, 2020). "The relevance of these in vitro results to human gastric cancer is supported by the positive correlation between IL-17RB and OCT4, NANOG, LGR5, and SALL4 mRNA expression in human gastric cancer tissues." (PMID 32373132, 2020). "Elevated mRNA levels of OCT4, NANOG, SOX2, LIN28, and CD133 have also been identified in tumorigenic hybrid cells derived from mesenchymal stem cells and gastric cancer cells." (PMID 28768501, 2017). "We confirmed that SP cells utilized in this study express candidate gastric cancer stem cell markers including CD44, CD133, and NANOG." (PMID 25379943, 2014). "This study expands on BATF2's role in gastric cancer, demonstrating how it interacts with PTEN to suppress the AKT/β-catenin/ABCG2 signaling pathway, impacting stem cell markers like ABCG2, CD44, SOX2, and NANOG, based on in vivo and in vitro analyses." (PMID 39629124, 2024). "When human umbilical cord MSCs and gastric cancer cells merge in vitro, tumorigenic hybrids are created that demonstrate increased expression of stemness markers, such as CD44, CD133, OCT4, SOX2, and NANOG." (PMID 39547513, 2024). "In a study on gastric cancer, it was shown that DDIT3 can directly upregulate the transcription factor CEBPB, thereby increasing the stemness of gastric cancer cells and the expression of stem cell markers: SOX2, NANOG, OCT4, and CD133." (PMID 38710698, 2024). "Furthermore, the negative correlation of PTGDR2 with mRNA expression of OCT4, NANOG, LGR5, and SALL4 in cancerous tissues also demonstrated the relevance of these in vitro results to gastric cancer." (PMID 38704736, 2024). "Furthermore, a cell fluorescence recovery assay revealed that transfection with Circ-0075305 or miR-708-5p mimic led to changes in the gastric cancer stem cell-related markers CD44 and NANOG; however, these effects were reversed by sh-RPRD1A." (PMID 38714724, 2024).
teratoma (23 papers, 2015 to 2025). A non-seminomatous germ cell tumor characterized by the presence of various tissues which correspond to the different germinal layers (endoderm, mesoderm, and ectoderm). "They used targeted integration to express an inducible caspase 9 activated by the BB homodimerizer at the end of the NANOG gene using a 2A sequence, showing the ability to prevent or ablate teratomas." (PMID 36189285, 2022). "We characterized iPSCs by demonstrating the gene expression of the PSC markers OCT4, SOX2, TRA-1-60, and NANOG, teratoma formation, and differentiation into three germ layers." (PMID 36614165, 2022). "The colonies isolated from sparse cultures of hiPSC-teratoma cells expressed NANOG and OCT3/4 strongly, and telomerase reverse transcriptase (TERT) weakly." (PMID 26069211, 2016). "It expressed genes involved in stemness (OCT3/4, SOX2 and NANOG), was able to generate teratoma in immunodeficient SCID mice and to differentiate into early mesodermal, endodermal and ectodermal cells as shown by the expression of specific markers." (PMID 27043207, 2016). "Furthermore, the mRNA expression of canine endogenous OCT4, SOX2, and NANOG significantly increased, confirming the multi-differentiation potential of cells after embryoid and teratoma formation." (PMID 40531862, 2025). "The results showed iPSC could express pluripotency markers such as OCT4, SOX2, and NANOG and form an embryoid body and a teratoma." (PMID 33224204, 2020). "Furthermore, none of colonies isolated from the soft agar gel on primary culture (passage 0) of teratoma cells, expressed NANOG and OCT3/4 in the expanded cultures." (PMID 26069211, 2016). "Overall, these cells presented different pluripotency features, such as teratoma and embryoid body formation, alongside the detection of pluripotency markers OCT4 and NANOG, as well as others, as recently reviewed." (PMID 32586372, 2020). "The isolated EF-iPSCs showed high expression of pluripotency markers, such as OCT4, NANOG, TRA-1-60, TRA-1-81, SSEA3, SSEA4, and AP, and underwent differentiation into three germ layers in vitro and typical teratoma formation in vivo." (PMID 31324753, 2019). "The isolated hiPSC colonies were cultured in E8 culture medium, and further verified by expression of pluripotency markers NANOG, SOX2, OCT4 and TRA-1-60, and formation of embryoid bodies (EBs) and teratoma with three germ layers." (PMID 29523209, 2018). "We also confirmed that all the patient-derived iPSC lines expressed the embryonic stem cell markers OCT3/4, SOX2, NANOG, REX1, MYC, and KLF4 and were capable of forming teratomas." (PMID 29088246, 2017). "Most importantly, NP cultures from all three lines demonstrated significantly low or undetectable levels of NANOG, SOX2 and OCT4 mRNA transcripts, which is essential in preventing teratoma formation in vivo." (PMID 25635918, 2015). "Previous studies have shown that AFMSCs obtained from early and second-trimester AF can express various ESCs markers such as OCT-4, SOX2, NANOG, SSEA4, and TRA1-81, which may raise the concern of teratoma formation post-transplantation." (PMID 38085460, 2024). "Furthermore, we demonstrated that NANOG and OCT4 expression remaining until stage III (day 15 of differentiation) completely disappeared when treated with YM155 and teratoma formation was effectively prevented by YM155 pretreatment in the in-vitro study." (PMID 28412976, 2017). "None of the grafts remained pluripotent (negative for NANOG) or formed teratomas." (PMID 35943218, 2022). "Interestingly, most teratoma sections were negative for the pluripotency markers OCT4A, LIN28, TRA-1-60 and NANOG, for which we have established specific and sensitive immunohistochemical detection protocols." (PMID 34326359, 2021).
teratoma (continued). "However, the decreased levels of NANOG and SOX2 observed upon HMGB1 or HMGB1/2 double KD had no impact on the pluripotency of hESCs, as revealed using a teratoma formation assay, in which no tangible deviation from the normally differentiated teratoma morphology was demonstrated." (PMID 33076532, 2020).
liver cancer (21 papers, 2013 to 2025). An epithelial or non-epithelial malignant neoplasm that arises from the liver. "RNAi-mediated NANOG knockdown has been successfully used to improve the chemosensitivity of HepG2 liver cancer cells to doxorubicin or oesophageal cancer cells to cisplatin." (PMID 40729003, 2025). "Recent studies have shown that YAP1 is highly expressed in liver cancer stem cells and its expression was positively correlated with the expression of stemness markers (NANOG, OCT-3/4, and CD133)." (PMID 36045416, 2022). "On the other hand, high expression levels of IGF-2 were observed in both NANOG+-liver cancer stem cells, which were isolated from patient-derived primary HCC cells and in HCC cell lines." (PMID 33669204, 2021). "The serum level of IL-6 is elevated in liver cancer patients who express high levels of NANOG and OCT4." (PMID 33669204, 2021). "Using a liver cancer mouse model in which tumor-initiating stem-like cells (TICs) were driven by NANOG expression, it was discovered that a high-cholesterol, high-fat Western diet resulted in transactivation of NANOG." (PMID 33804114, 2021). "In line with this, the treatment of breast and liver cancer cell lines with FAK inhibitor 14 has been found to decrease NANOG expression." (PMID 31212816, 2019). "Aberrant activation of STAT3 has been demonstrated to maintain the CSC population of liver cancer through increased expression of NANOG." (PMID 28617312, 2017). "NANOG inhibition suppresses hepatic cancer stem cells propagation." (PMID 37582956, 2023). "NANOG is a fundamental transcription factor to maintain the stemness of hepatic cancer stem cells." (PMID 37582956, 2023). "Several studies have revealed the importance of NANOG as a CSC maintainer in liver cancer and CRC." (PMID 30804456, 2019). "Further analysis using RT quantitative PCR (qPCR) revealed that the expression of the pluripotent transcription factors OCT4, NANOG, and SOX2 was significantly higher in both the human PSCs than in a somatic liver cancer cell line (HepG2215)." (PMID 39040044, 2024). "The expression of SOX2 and NANOG, 2 key stem cell biomarkers regulating cell self‐renewal, further verified the role of SHH/Gli signalling in CD90+ liver cancer stem cell regulation in this study." (PMID 29722127, 2018).
head and neck squamous cell carcinoma (17 papers, 2015 to 2025). A squamous cell carcinoma that arises from any of the following anatomic sites: lip and oral cavity, nasal cavity, paranasal sinuses, pharynx, larynx, and salivary glands. "Among them, NANOG was proposed as an independent predictor of better clinical outcome in head and neck squamous cell carcinoma." (PMID 36980171, 2023). "A groundbreaking report confirmed that high expression of CAF-specific VEGFA, PGE2S, COX2, EGFR, CCL2, and NANOG was considered as the culprit of CDDP resistance development in head and neck squamous cell carcinoma (HNSCC)." (PMID 36359776, 2022). "The increased expression of the FOS gene can trigger the VEGF (vascular endothelial growth factor) and enhance NANOG and c-myc genes in head and neck squamous cell carcinoma." (PMID 35216085, 2022). "Targeting NANOG in head and neck squamous cell carcinoma-derived spheroid cells significantly inhibits tumor aggressiveness and increases chemosensitivity to cisplatin; perhaps targeting NANOG within mHNcSCC would have a similar effect on these parameters." (PMID 32850316, 2020). "NANOG has been found overexpressed in various human cancers, including head and neck squamous cell carcinomas." (PMID 31484317, 2019). "A very recent meta-analysis has suggested the prognostic potential of CSC markers, particularly CD133, NANOG, and OCT4, in head and neck squamous cell carcinoma." (PMID 37109090, 2023). "Several CSC markers have been studied in head and neck squamous cell carcinomas (HNSCC), including the pluripotency factors NANOG, SOX2, and OCT4; however, their clinical significance is still unclear." (PMID 32635524, 2020). "Additionally, in head and neck squamous cell carcinoma (HNSCC), ZSCAN4 played an important role in facilitating chromatin remodeling and activating cancer stem cell factor expression, including OCT3/4, NANOG, KLF4, and SOX2." (PMID 36841776, 2023). "In head and neck squamous cell carcinoma, human RNA helicase DDX3 could modulate cisplatin resistance via ALKBH5-mediated m6A demethylation of FOXM1 and NANOG." (PMID 35279083, 2022). "NANOG also plays a role in the self-renewal of CD24+ cancer stem cells in hepatocellular carcinomas and has been found aberrantly expressed in a variety of human cancers, including head and neck squamous cell carcinomas (HNSCC)." (PMID 33233861, 2020). "The early transcription factors NANOG, OCT4, and SOX2, which play pivotal roles in the maintenance of pluripotency and self-renewal ability in both embryonic and adult stem cells, have also been reported as key regulation factors in the CSCs of head and neck squamous cell carcinoma (HNSCC)." (PMID 26626427, 2015).
oral squamous cell carcinoma (17 papers, 2014 to 2026). "High levels of NANOG expression were associated with increased malignancy, and this has been observed in many types of cancers, including oral squamous cell carcinoma." (PMID 41463190, 2025). "For example, SOX2, OCT4, and NANOG were found to be overexpressed in several cancers, including breast, prostate, and oral squamous cell carcinoma, and their expression levels were associated with tumor transformation, tumourigenicity, and tumor metastasis." (PMID 29868483, 2018). "AGR2 expression was also shown to have a strong positive correlation with nanog homeobox (NANOG) in oral squamous cell carcinoma." (PMID 36482387, 2022). "NANOG, a key regulator of pluripotency and self-renewal in embryonic and adult stem cells, is frequently overexpressed in multiple cancers, including oral squamous cell carcinoma (OSCC)." (PMID 31484317, 2019). "In the present study, NANOG expression in oral squamous cell carcinoma (OSCC) was examined to determine its potential clinical significance." (PMID 24348816, 2014). "NANOG is a stem cell transcription factor that is believed to play an important role in the development of oral squamous cell carcinoma (OSCC), but there is limited data regarding the role of long non-coding RNAs (lncRNAs) and microRNAs (miRNAs) in the regulation of NANOG expression." (PMID 33643897, 2020). "Similarly, a recent study clearly demonstrated that inhibition of NF-kB reduces the expression of stem cell transcription factors SOX-2, NANOG, and Oct-4 in CSCs that present overexpression in several cancers, including breast, prostate, and oral squamous cell carcinoma." (PMID 33218351, 2020). "In a study of oral squamous cell carcinomas (OSCC), CSC-like markers expressed in cisplatin resistant oral carcinomas such as NANOG and OCT-4 became expanded during the acquisition of cisplatin resistance in OSCC." (PMID 29069808, 2017). "Additionally, it explores impacts on stem cell genes, SRY-box transcription factor 2 (SOX2), octamer-binding transcription factor 4 (OCT4), and Nanog homeobox (NANOG), linking tobacco to cancer stem cell proliferation and metastasis (e.g., oral squamous cell carcinoma)." (PMID 41782786, 2026). "Results of previous studies suggest that NANOG may be an important prognostic biomarker in oral squamous cell carcinoma (OSCC), but there are contradictory results regarding NANOG expression patterns on mRNA and protein levels, and the mechanisms of its regulation are poorly understood." (PMID 32733958, 2020).
lung adenocarcinoma (16 papers, 2010 to 2025). A carcinoma that arises from the lung and is characterized by the presence of malignant glandular epithelial cells. "The induction of stem cell transcription factors like OCT4 and NANOG enhances the properties of cancer stem cells and contributes to the malignancy of lung adenocarcinoma." (PMID 40287470, 2025). "The induction of stem cell transcription factors OCT4 and NANOG enhances CSCs’ properties and elevates the malignancy of lung adenocarcinoma." (PMID 38132948, 2023). "Co-expression of OCT4 and NANOG in lung adenocarcinoma enhances cell proliferation and motility and decreases their differentiation by inducing cancer stem cell-like properties[28 ▶]." (PMID 32429647, 2020). "On the contrary, ectopic expression of OCT4 and NANOG in lung adenocarcinoma induced cancer stemness and EMT." (PMID 31867270, 2019). "Both NANOG and OCT4 overexpressions are associated with both advanced cancer stage and decreased survival in oral squamous cell and lung adenocarcinomas." (PMID 27225481, 2016). "Interestingly, ectopic overexpression of OCT4 and NANOG in lung adenocarcinoma cells activated SLUG and enhanced sphere formation, drug resistance, tumor-initiating capability, and promoted EMT, confirming that OCT4/NANOG signaling controls EMT." (PMID 34771704, 2021). "Moreover, a previously characterized OCT4/SOX2/NANOG embryonic stem cell expression signature effectively separated SCCs from lung adenocarcinomas when analyzed in publicly available NSCLC microarray datasets." (PMID 20161759, 2010). "Immunohistochemical (IHC) staining performed on 12 lung adenocarcinoma (LA) tissue samples showed protein expression of OCT4, NANOG, SOX2, KLF4 and c-MYC, and the CSC marker CD44." (PMID 34685477, 2021). "Overexpressions of NANOG and OCT4 also afford lung adenocarcinoma cells a high tolerance to cisplatin." (PMID 27225481, 2016). "Recently, ectopic expression of OCT4 and NANOG was shown to enhance malignancy and induce EMT in lung adenocarcinoma cell lines." (PMID 21952072, 2011). "We find that NANOG is not expressed at a meaningful level in human lung adenocarcinoma (ADC), as well as in human lung invasive mucinous adenocarcinoma (IMA)." (PMID 33439550, 2021). "Besides, lung adenocarcinoma cells with P4HA1 knockdown showed decreasing OCT4, SOX2, NANOG protein levels." (PMID 34659558, 2021). "In lung adenocarcinomas, expression of SOX2 but not NANOG was detected in approximately 50% of stage I tumors, whereas another study reported NANOG expression without SOX2, hence suggesting a SOX2-independent regulatory mechanism of NANOG expression in these tumors." (PMID 32635524, 2020).